CD4 (CD4 molecule)
Diseases named in the same sentence as CD4 in open-access papers (continued):
Sharing a sentence is not in itself a finding about the gene and the disease.
melanoma (continued). "In melanoma — a tumor type known to derive durable clinical benefit from ICB — the IED-related gene set was also expressed by a cluster of cells with fibroblast features, in addition to CD8+, CD4+, and NK cells." (PMID 36099049, 2022). "Although other studies reported GILT expression in human melanoma tumors by immunohistochemistry, our study suggests that infiltrating cells, but not metastatic melanoma, express GILT, and that GILT-expressing melanomas are a better target for CD4+ T cells." (PMID 35162988, 2022). "In order to test this hypothesis, we analyzed CpG5 methylation levels in melanoma cell lines (N = 59), cell lines of melanocytes (N = 3), and peripheral leukocytes (monocytes, B cells, CD8+ and CD4+ T cells) from healthy donors (N = 28)." (PMID 35410311, 2022). "In vivo experiments showed that GM could effectively inhibit the expression of tyrosinase, regulate the proportion of CD4+ T cells, CD8+ T cells, and regulatory T cells (Treg cells) in tumors, and significantly suppress melanoma growth." (PMID 35875081, 2022). "Additionally, OX40 agonist engagement in the setting of chemotherapy-induced lymphopenia with adoptively transferred tumor-specific CD4+ T cells was effective in treating B16 melanomas and chimeric B16:B78H1 melanomas." (PMID 36159781, 2022). "In this same study, B16 melanoma cells increased MHC-II expression in vivo in an IFNγ-dependent manner, and the adoptively transferred CD4+ T cells could kill tumor cells in vitro and reject challenge tumors in vivo in an MHC-II-dependent manner." (PMID 36159781, 2022). "In order to unveil the pathological morphology and immunological landscape within tumor tissues from the combination groups, we further observed the H&E and immunofluorescence (blue-nucleus, red-CD4, green-CD8, pink-CD11c) staining of B16-OVA melanoma orthotopic tumor." (PMID 35547749, 2022). "Distinct immune signatures, such as CD8+PD-1+ T cells, CD8+ effector memory (CD8+CD45RA−CD45RO+CCR7−) T cells, activated CD4+ T cells (CD4+CD38+HLA-DR+), and NK cells (CD16+CD56+CD38+HLA-DR+) showed the treatment response and immune-related adverse events in melanoma patients in ICI therapy." (PMID 36569825, 2022). "Previous studies described CD4+CD8+ cells as effector anti‐tumor T cells in a series of tumors for example, cutaneous T‐cell lymphoma, nodular lymphocyte‐predominant Hodgkin lymphoma, and melanoma." (PMID 35451108, 2022). "The Lipo-MERIT trial demonstrated strong CD4+ and CD8+ T cell induction along with durable objective clinical benefit in unresectable melanoma patients treated with a poly-antigenic liposomal RNA vaccine with or without combination with anti-PD1 checkpoint blockade therapy." (PMID 34728792, 2022). "The percentage of CD3+, CD4+, CD8+ T cells, macrophages, and natural killer cells increased after radiation, resulting in reduced tumour growth and prolonged overall survival in the three different mouse models of melanoma." (PMID 34732697, 2021). "In CT26 colon cancer cells and B16-F10 melanoma cells, targeting PIK3C3 with siRNA or PIK3C3 inhibitors reduced autophagy and tumor growth and improved mouse survival by inducing the infiltration of natural killer, CD8+, and CD4+ T effector cells." (PMID 34681622, 2021). "Robust tumor antigen-specific CD4+ and CD8+ T-cell responses were evident, and clinical benefits were observed in this trial, favoring the use of mRNA-electroporated dendritic cell vaccines against melanoma." (PMID 34696168, 2021). "Consistently, a correlation matrix profiling of gene mRNA expression in TCGA collection of melanoma tumors showed that CD40 expression significantly and positively correlates with CD4 and CD8 infiltrates, as well as with type 1 cytokine responses based on IFNγ and GzmB expression patterns." (PMID 34092233, 2021). "Both CD4+ and CD8+ T-cells specific for PRAME, a melanoma antigen, could be expanded from the peripheral blood of healthy donors." (PMID 34526999, 2021).
melanoma (continued). "As far as other co-stimulation, while ICOS expression has been seen in human melanoma TIL for cytotoxic CD4+ T cells, this is not universally seen across the other cancer/non-cancer studies." (PMID 34910940, 2021). "To determine whether Th and Tc cells are required for the anti-melanoma activity of RGS, we conducted depletion experiments of CD4 and/or CD8 cells." (PMID 34092233, 2021). "In models of CT26 CRC cells and B16-F10 melanoma cells, targeting PIK3C3 with SAR405 inhibited autophagy, significantly decreased tumor growth, and improved mouse survival by inducing the infiltration of natural killer, CD8+, and CD4+ T effector cells." (PMID 34681622, 2021). "Interestingly, the frequency of intratumoral CD3+ T cells, CD8+ T cells, total CD4+ T cells, Treg, and M-MDSC remained unchanged upon the therapy in both melanoma lesions." (PMID 33578808, 2021). "Second, to assess whether alloreactive T cells specific to the B6 host are important for eliminating tumors, B6 CD4+ T cells were stimulated with BALB/c GM-DCs and injected into B16F1 melanoma cells." (PMID 34625113, 2021). "Although no significant modulations in CD4+ regulatory T cells (Treg) were seen in any patient after therapy, we observed a substantial increase in this cell subset early in the treatment of melanoma patients, and mainly in non-responder ones." (PMID 34777395, 2021). "Interestingly, a recent study showed that cDC1s are also required for earlier CD4+ T cell priming, and CD40 signaling in cDC1 is critical for CD8+ T cell priming and CD4+ T cell activation against fibrosarcoma and melanoma." (PMID 34283809, 2021). "Significantly increased frequencies of CD25+ cells that include both FoxP3+ and FoxP3- populations, were observed for CD4+ (p = 0.01) and CD4-CD8- (p = 0.0038) T cell subsets in blood from canine melanoma patients (n = 16) compared to healthy controls (n = 20)." (PMID 34926643, 2021). "These modified DCs could induce substantial levels of functional CD4+ and CD8+ cells in melanoma patients." (PMID 33692796, 2021). "This bowel injury allowed the recruitment, activation, and mobilization of CCR7-expressing dendritic cells to Peyer patches, mLN, and tdLN, culminating in the massive infiltration of IFNγ-producing CD4+ and CD8+ TILs and tumor control of poorly immunogenic melanoma." (PMID 33262469, 2021). "The TIMER analysis showed that MCM3 was closely correlated with B cells and CD4+ and CD8+ T cells, which may provide a new approach to immunotherapy for melanoma." (PMID 34490114, 2021). "In the CD4+ T-cell compartment, 51 signatures were detected to be differentially expressed pre-treatment between responders and non-responders in melanoma (cluster 204, cluster 205, cluster 206 and cluster 220)." (PMID 34071888, 2021). "The role of CD4+ T cells in ICB continues to be an active area of exploration as markers of long-term survival in melanoma, though not all studies have made distinctions between regulatory and effector CD4+ cells." (PMID 35087529, 2021). "It has been reported that CD4 + and CD8 + lymphocytes secreting IL-17 promote melanoma regression." (PMID 34784974, 2021). "The levels of nuclear enriched abundant transcript 1 (NEAT1), miR-485-5p, and absent in melanoma 2 (AIM2) in CD4+ T cells were determined using real-time quantitative polymerase chain reaction (RT-qPCR)." (PMID 34696702, 2021). "Importantly, there was a negative correlation between the expression of KRT16 and the infiltration of CD8+ T cells, CD4+ T cells, macrophages, neutrophils, and dendritic cells, which is consistent with previous findings and might provide insights into the immunotherapy of melanoma patients." (PMID 33441834, 2021). "Last, efficient CD4+ T-cell priming was observed with B3 and F6 pro-B cell leukemia cells but not with B16 melanoma or MCA-38 colon adenocarcinoma cells, although all these tumor cell lines can cross-dress DCs." (PMID 32313208, 2021).
melanoma (continued). "A study of DHA in melanoma showed that DHA induced the proliferation of IFN-γ+CD8+ T cells in tumor microenvironment and mouse spleens, while the number of CD4+CD25+Foxp3+ T cells and IL-10+CD4+CD25+ T cells returned to normal, thus enhancing the anti-tumor immunity of mice." (PMID 33613116, 2021). "The specific metabolic environment in these organs also affects the energy metabolism and effector function of different T cell populations, such as shown for instance in the melanoma TME, in which low glucose levels inhibit aerobic glycolysis and the tumoricidial function of CD4+ and CD8+T cells." (PMID 34135885, 2021). "In a previous study, the authors had treated six patients with advanced melanoma and showed, that despite including HLA class I-binding peptides (for CD8+ T-cell recognition) in the vaccine design, superior CD4+ T-cell responses directed against the patients’ neoantigens was observed." (PMID 34335558, 2021). "Resting mast cells, resting dendritic cells, and memory CD4+ T cells showed no significant OS in melanoma patients." (PMID 32931642, 2020). "For example, PEG-PLA NPs [poly(ethylene glycol)-block-poly(D,L-lactide)] loaded with CTLA-4 siRNA efficiently restored the T-cell functions by downregulating CTLA-4 level and increasing the CD4+ and CD8+ T cell populations as well as inhibited tumor growth in mice with melanoma (Li S.-Y." (PMID 33409265, 2020). "Analyzing the expression of the early activation marker of T‐cells, CD69, a significant increase was observed for the Ar/O2, He, and He/O2 conditions when comparing splenic CD4+ T‐cells cultured in the presence or absence of melanoma cells." (PMID 32440479, 2020). "Re‐stimulation of splenocytes isolated from these mice with B16F10 melanoma cells revealed a significant increase of the early activation marker CD69 in CD8+ but not in CD4+ T‐cells." (PMID 32440479, 2020). "Inhibition of γδT cells using an anti‐γδTCR mAb in aged mice significantly reduced the mean survival time from 48.63 to 34.38 days after the B16/F10 melanoma challenge, but not the depletion of CD4+T cells by anti‐CD4 mAb treatment." (PMID 31903715, 2020). "CD4+ T cells infiltrated into B16 melanoma tissue, but not splenic CD4+ T cells in the same mice, exhibited substantially higher LSP1 expression than splenic T cells of non-tumor-bearing mice." (PMID 33020243, 2020). "The inhibitory function of VISTA in anticancer immunity was demonstrated in mice transplanted with melanoma, in which blocking of VISTA induced antitumor immunity by increasing tumor-specific CD4+ and CD8+ T cells and decreasing FoxP3+ regulatory T cells in the tumor microenvironment." (PMID 32873829, 2020). "Here, we found CD4+ T cells with polyfunctional helper and cytotoxic activity among TCR transgenic cells in models of adoptive transfer and within polyclonal CD4+ T cell populations in the mouse fibrosarcoma and human melanoma tumor microenvironment." (PMID 31924474, 2020). "Here, although melanoma (the tumor with the highest average TMB) presented with the greatest CD8+ TIL response, within melanoma a high TMB did not appear to represent a major driver for the accumulation of either tumor-reactive CD8+ TILs or CD4+ TILs." (PMID 33198174, 2020). "An increase in IFN-γ+ CD8+ T cells (~2-fold fold) in dLNs in CRT-NP, CFUS, and FUS were observed, but not IFN-γ+ CD4+ T cells indicating the proliferation of melanoma specific cytotoxic immune cells." (PMID 32206098, 2020). "Also, low levels of IL‐17A and high levels of IFN‐γ production in lung CD4+T and NKT cells were detected in the aged mice after the B16/F10 melanoma challenge." (PMID 31903715, 2020). "Recent reports that emphasize the role of CD4+ T cells in determining the clinical outcome of immune checkpoint blockade in patients with NSCLC and melanoma are of particular relevance in the context of the UV1 vaccine, which is designed to elicit CD4+ T cell responses." (PMID 33324397, 2020).
melanoma (continued). "In both lung cancer and melanoma patients, elevated baseline frequencies of CD4 + Foxp3- T cells expressing PD-1 and/or lack of their significant down-modulation after PD-1 blockade resulted in a higher risk of death." (PMID 32460897, 2020). "An earlier study also detected CD4+ T cell responses to HLA class II-restricted epitopes from BRAF V600E in patients with BRAF V600E melanoma, although not in the context of clinical response after immunotherapy." (PMID 32117272, 2020). "In the C51 colon carcinoma model, changes in total numbers of CD8+ T cells, NK cells, and immunosuppressive CD4+ Tregs in spleen and lymph nodes were similar to those in the B16 melanoma model (data not shown)." (PMID 30808414, 2019). "To this end, we synthesized two multivalent LeY vaccines incorporating the CD4 and CD8 melanoma-specific gp100 antigen using two generations of well-defined, commercially available PAMAM dendrimer scaffolds which consist of branched subunits of amide and amine functionality." (PMID 31534520, 2019). "To determine whether TRAPs impact CD4+ T cell function, we first isolated TRAPs from the culture supernatants of mouse B16F10 melanoma cells." (PMID 31300052, 2019). "The depletion of Tregs has also been shown to delay tumor growth upon vaccination in melanoma-bearing mice, while depletion of the whole CD4 T-cell population showed no such effect." (PMID 31333674, 2019). "The bulk CD4+ CTLs in our cultures included large numbers of naïve T cells, whose cytolytic activity potential was significantly enhanced after CTLA-4 blockade with checkpoint inhibitors in a mouse model of combined immunotherapy for melanoma." (PMID 30783516, 2019). "Moreover, adoptive transfer of BTRAP + SN/TTRAP decreased the numbers of IFN-γ+ CD8+ and CD4+ T cells induced by DCOVA vaccination and promoted the growth of B16F10 melanoma cells and their metastasis to the lung." (PMID 31300052, 2019). "The interaction between highly constitutive expression of MHC class II molecules at the surface of melanoma cells and LAG-3 greatly expressed on melanoma-specific CD4+ T cells elicits a local TNF-rich inflammatory environment, reducing the cytotoxic CD8+ T cell responses." (PMID 32039024, 2019). "In order to characterize how melanoma tumours influence the CD4+ CD25− T-cells, healthy donors’ pre-activated primary CD4+CD25− T-cells were co-cultured with human cutaneous melanoma cell lines, including DFB, A375, and SK-MEL-28 (V600E) and BE and SK-MEL-2 (V600 wt), for five days." (PMID 31434983, 2019). "In anti-4-1BB–treated B16-SIY melanoma-bearing mice, the frequency of CD73+ cells among both tumor-infiltrating CD4+ and CD8+ T cells was considerably reduced, which was explained largely by a favorable expansion of CD73− T cell compartment in response to 4-1BB ligation." (PMID 30635578, 2019). "Similarly, CD4+ T cells were immunized with OVA-Dex, and exosomes derived from the immunized CD4+ T cells stimulated a long-term, OVA-specific CD8+ T cell memory response, and immunity against melanoma cells in vitro and in vivo." (PMID 31615107, 2019). "Mice vaccinated with irradiated B16 melanoma cells and treated with checkpoint signal blockade including anti-CTLA-4 and/or anti-PD-1resulted in marked resolution of solid tumor burden and increased CD4+/CD8+ to Treg ratio in the tumor." (PMID 31681327, 2019). "This glycoliposome-based vaccine could boost CD4+ and CD8+ T cell responses when the melanoma antigen MART1 was co-delivered." (PMID 31695803, 2019). "Previous, we established a novel therapeutic approach to tumour of cryo-thermal therapy, which can induce durable anti-tumour memory immunity mediated by CD4+ T cell, and contribute to prolonged survival in B16F10 murine melanoma model and 4T1 murine mammary carcinoma." (PMID 31519961, 2019). "The PD-1 blockade increased CD4+ tumor-infiltrating lymphocyte (TIL) numbers in B16F10 melanoma with FTO knockdown, but not in control cells." (PMID 31239444, 2019).
melanoma (continued). "The greater extend of CD4+ TCR repertoires restrictions with higher numbers of both restricted Vβ-gene families and prominent peaks reveal broader clonal CD4+ T-cell responses in melanoma patients." (PMID 31275310, 2019). "We then analyzed how CTLA4 blockade might affect TCR repertoires in the CD4+ and CD8+ T-cell subsets in 17 melanoma patients treated with CTLA4 antibody." (PMID 31275310, 2019). "Concurrently with a robust destruction to primary melanoma, CAH‐mediated PDT treatment elicits durable and systemic immunological effects to combat metastases and recurring tumors depending on the activation of CD4+CD8+ double positive T cells." (PMID 30886812, 2019). "The importance of the immune system for tumor control seen in the Rnf5−/− mice was confirmed upon administration of antibodies depleting CD4+ or CD8+ T cells, which abrogated the ability of Rnf5−/− mice to inhibit melanoma tumor growth, with a small additive effect upon CTLA4, but not PD-1 blockade." (PMID 30940817, 2019). "The mean survival time for untreated, WT, and CD4-depleted mice were 19, 28, and 30 days, respectively, pointing out the therapeutic effect of PCI-based vaccination against melanoma, independent of CD4 T cells." (PMID 31333674, 2019). "Melanoma tumor cells express antigens that are recognizable by the host CD8+ T cells, which kill tumor cells, and whose induction and recruitment are mediated by CD4+ helper T cells." (PMID 29581861, 2018). "To determine how these CD4+Foxp3+IL-10+ cells affect the anti-metastatic effects of metformin, we injected C57BL/6J mice with anti-CD25 1 day prior, and 1 and 7 days after B16F10 melanoma inoculation." (PMID 29899823, 2018). "Percentages of naive and memory CD4+ T cells were not different when comparing old melanoma patients to age-matched controls." (PMID 29546435, 2018). "CD49a expression by CD103+CD4+ and CD103+CD8+ TILs may allude to this, as CD49a expressing CD103+CD8+ TILs were the most potent killers of tumor cells in a mouse model of melanoma and CD49a defines cytotoxic CD8+ TRM in skin." (PMID 30505306, 2018). "In contrast, the percentage of PD-1 expressing CD4+ T cells was not modulated in old melanoma patients." (PMID 29546435, 2018). "In contrast, no modulation of Ki-67 was observed in CD4+ T cells of old melanoma patients when compared to their age-matched controls." (PMID 29546435, 2018). "Furthermore, it has been demonstrated that an increased frequency of ICOS+ CD4+ T cells, sustained over a period of 12 weeks of anti-CTLA-4 therapy, correlates with improved OS in melanoma patients." (PMID 29494517, 2018). "To functionally determine whether T cells are involved in the anti-metastatic effect of metformin, we injected B16F10 melanoma cells into C57BL/6 (WT), RAG1−/−, CD8−/−, and CD4−/− mice." (PMID 29899823, 2018). "Taken together, the CD4+ T-cell compartment of young melanoma patients, but not old melanoma patients, shows increased expression of the checkpoint inhibitor PD-1 but not CTLA-4." (PMID 29546435, 2018). "In contrast, we observed no clear modulation of CTLA-4 in CD4+ T cells of melanoma patients and healthy controls." (PMID 29546435, 2018). "Collectively, the more robust CD4+ and CD8+ T cell populations and infiltration to tumor sites of the Per1/2−/− mice suggests that clock-regulated immune function plays an important role in sensitizing melanoma tumors to cisplatin treatment." (PMID 29581861, 2018). "Mice lacking CD4 T cells were unresponsive to CTLA-4 antibody treatment when challenged with a transplantable melanoma cell line." (PMID 29032503, 2018). "This was accompanied with increased percentages of memory CD4+ T cells expressing HLA-DR, Ki-67, and PD-1 in young melanoma patients in comparison to the age-matched controls, but not in old patients." (PMID 29546435, 2018).